SATB1 (SATB homeobox 1)
Diseases named in the same sentence as SATB1 in open-access papers (continued):
Sharing a sentence is not in itself a finding about the gene and the disease.
diabetes (1 paper, 2009). "Here we report that hypothalamic expression of CREB-binding protein (CBP) and CBP-binding partner Special AT-rich sequence binding protein 1 (SATB-1) is highly correlated with lifespan across five strains of mice, and expression of these genes decreases with age and diabetes in mice." (PMID 19924292, 2009). "Expression of SATB-1 accounts for almost as much variance of lifespan and decreases with age and diabetes but is not induced by bDR, and dve-1 RNAi (ortholog of SATB-1) only partly blocks lifespan extension by bDR and the daf-2 mutation." (PMID 19924292, 2009). "Similarly, among genes whose expression was examined (including those previously implicated in mediating protective effects of DR), expression of only CBP, SATB-1, and HSF-1 decrease with age and diabetes." (PMID 19924292, 2009). "Similarly, cortical expression of CBP, SATB-1, and HSF-1 but not other genes implicated in influencing lifespan (e.g., the daf-16 ortholog FOXO3A) decreased with age and diabetes, a disease that mimics many effects of aging." (PMID 19924292, 2009).
ductal carcinoma (1 paper, 2012). "Nevertheless, it is remarkable that SATB1 was closely associated with HIF-1α in HR-positive and the whole cohort of ductal carcinoma; the factors with involvement of SATB1 and HIF-1α caused a major portion of variation in both groups, especially, in HR-positive tumours." (PMID 22424533, 2012). "In the group of ductal carcinoma, we find that HIF-1α participates in two factors: factor 1 (i-Grade) along with Ki67 and factor 2 - along with SATB1." (PMID 22424533, 2012). "Second, in the group of HR-positive ductal carcinoma, HIF-1α participates in the most important factor 1 along with SATB1 providing factor loadings opposite to those of AR, ER and BCL2, independently of Ki67 expression (factor 3)." (PMID 22424533, 2012). "First, in the group of ductal carcinoma, we find that HIF-1α participates in two factors: factor 1 (i-Grade) along with Ki67 and factor 2 - along with SATB1." (PMID 22424533, 2012).
duodenal adenocarcinoma (1 paper, 2014). A carcinoma that arises from glandular epithelial cells of the duodenum. "The results from this study provide a first demonstration of the expression and prognostic value of SATB1 in pancreatic, distal bile duct, ampullary and duodenal adenocarcinoma." (PMID 25323550, 2014). "The expression and prognostic significance of SATB1 and SATB2 in pancreatic, distal bile duct, ampullary or duodenal adenocarcinomas has not yet been reported." (PMID 25323550, 2014).
eosinophilia (1 paper, 2019). "Thus, reduced SATB1 expression in SS and L-HES may facilitate both eosinophilia and enhanced T cell proliferation." (PMID 31489115, 2019).
fibrosis (1 paper, 2016). the formation of excess fibrous connective tissue in an organ or tissue in a reparative or reactive process. "To confirm the role of SATB1 in HBV-related liver fibrosis, we silenced SATB1 in vivo in a CCl4-induced fibrosis model of HBV-Tg mice." (PMID 27883059, 2016). "First, hepatic SATB1 expression is positively upregulated in patients and mouse model with HBV-related fibrosis." (PMID 27883059, 2016). "Similarly, the mRNA and protein levels of SATB1 were both enhanced in CCl4-induced fibrosis model, compared with the control group, yet mRNA level of SATB1 in CCl4-induced fibrosis model at 4 weeks was not significantly increased." (PMID 27883059, 2016).
gastric adenocarcinoma (1 paper, 2019). "Therefore, we assessed the expression of HER2, NF-κB, and SATB1 in a total of 104 gastric adenocarcinomas and 30 normal gastric samples and correlated the expression patterns with each other and with some clinicopathological variables." (PMID 31737131, 2019).
gastric tumours (1 paper, 2019). "The results were consistent, and SATB1′s overexpression in gastric tumours was associated with a significantly worse survival of the patients." (PMID 31450715, 2019). "All these studies clearly showed the prognostic value of SATB1′s expression in gastric tumours." (PMID 31450715, 2019). "Additionally, they revealed that SATB1′s expression was positively correlated with the HER2 level in gastric tumours." (PMID 31450715, 2019). "The authors observed a significant SATB1 overexpression in gastric tumours on both the protein and mRNA levels as compared to non-malignant tissue samples." (PMID 31450715, 2019).
Hyperkeratosis (1 paper, 2021). Hyperkeratosis is a histopathological term defining a thickened stratum corneum and may be present in many different skin conditions, with many possible overlaps. "SATB1 and p63, transcription and remodelling factors encoded by SATB1 and TP63, may contribute to the phenotype of hyperplasia and hyperkeratosis." (PMID 34322157, 2021).
invasive mammary carcinoma (1 paper, 2013). "In addition, knockdown of endogenous plakoglobin in the non-invasive mammary carcinoma MCF-7 cells (MCF-7-shPG) resulted in increased SATB1 mRNA and protein." (PMID 24260116, 2013).
liver fibrosis (1 paper, 2016). "In this work, we provided different lines of evidence supporting a direct causal link between SATB1 activation in hepatocytes and liver fibrosis." (PMID 27883059, 2016). "Therefore, distinct pathological basis and effector cells may determine the action of SATB1 in liver fibrosis." (PMID 27883059, 2016). "However, whether SATB1 in impaired hepatocytes exerts an effect on liver fibrosis remains unknown." (PMID 27883059, 2016).
microcephaly (1 paper, 2025). A congenital or acquired developmental disorder in which the circumference of the head is smaller than normal for the person's age and sex. "The truncated Satb1 protein leads to various physical and behavioral abnormalities, many of which resemble symptoms observed in patients, including microcephaly, postnatal developmental delay, ID, hypotonia, deficient cognitive and social abilities, and altered EEG." (PMID 40571781, 2025). "The presence of microcephaly in Satb1 mutant rats prompted us to investigate whether this microcephaly was caused by defective neurogenesis during the embryonic stages." (PMID 40571781, 2025). "In addition, the clinical characteristics associated with SATB1 variants include microcephaly, epilepsy, endocrine/metabolic abnormalities, and facial dysmorphisms." (PMID 40571781, 2025). "In addition, as microcephaly has been reported in some SATB1 mutant carriers and Satb1 is widely expressed in the developing cerebral cortex, we speculated that Satb1 mutation may affect cortical development." (PMID 40571781, 2025). "We showed that Satb1 mutant caused growth retardation, microcephaly, altered ultrasonic vocalization and delayed neurobehavioral development in mutant pups as well as social and cognitive behavior deficits in adult mutants, mimicking the typical clinical characteristics of SATB1-associated NDDs." (PMID 40571781, 2025). "Collectively, these results indicate that Satb1 is involved in the proliferation of neural stem cells/progenitors in the neurogenic region and that reduced proliferation may contribute to the microcephaly of Satb1 mutant rats." (PMID 40571781, 2025).
multiple sclerosis (1 paper, 2019). A progressive autoimmune disorder affecting the central nervous system resulting in demyelination. "Furthermore, a single nucleotide polymorphism (rs11719975) in a region near the human SATB1 gene has been recently associated with multiple sclerosis, suggesting an unappreciated link between SATB1 and the pathogenic function of effector T cells in the central nervous system of the patients." (PMID 30710091, 2019).
Neurodevelopmental delay (1 paper, 2025). "Clinical case reports have revealed that almost all individuals with SATB1 mutations exhibit neurodevelopmental delay, most suffer from ID, and some are diagnosed with behavioral disturbances, including ASD-related behaviors." (PMID 40571781, 2025).
oesophagal cancer (1 paper, 2023). "Its expression is upregulated by SATB1 stimulation, causing oncogenic effects and inducing oesophagal cancer development." (PMID 37543674, 2023).
oral squamous cell carcinoma (1 paper, 2017). "SATB1 promotes tumor metastasis in oral squamous cell carcinoma." (PMID 29050307, 2017).
periampullary adenocarcinoma (1 paper, 2014). An adenocarcinoma that arises from the periampullary region. "Therefore, the indication of a treatment predictive value of SATB1 expression in periampullary adenocarcinoma is of high potential clinical relevance and merits further validation in additional patient cohorts." (PMID 25323550, 2014). "Immunohistochemical expression of SATB1 and SATB2 was analysed in tissue microarrays with primary tumours and a subset of paired lymph node metastases from 175 patients operated with pancreaticoduodenectomy for periampullary adenocarcinoma." (PMID 25323550, 2014). "The prognostic value of SATB1 and SATB2 expression in periampullary adenocarcinoma has not yet been described." (PMID 25323550, 2014).
peripheral nerve injury (1 paper, 2020). Injury to a peripheral nerve. "In peripheral nerve injury, lncRNA-nuclear enriched abundant transcript 1 rich nuclear transcription factor 1 (NEAT1) promotes the proliferation and migration of Schwann cells by modulating the miR-34 a/SATB1 axis." (PMID 32323054, 2020).
pituitary hormone deficiency (1 paper, 2025). "A naturally occurring mutation of human PIT1 (R271W) that causes combined pituitary hormone deficiency fails to associate with SATB1 and β-catenin." (PMID 41036778, 2025).
rhabdomyosarcoma (1 paper, 2018). A rare aggressive malignant mesenchymal neoplasm arising from skeletal muscle. "Only 2 (CBEP3 and SATB1) out of 100 genes that are down regulated in YAP1 S127A and KRAS G12V-Cdkn2a-null induced rhabdomyosarcoma overlap with the bottom 100 genes whose low expression is best associated with poor survival in 18,000 cases of human cancer." (PMID 30353028, 2018).
serous carcinomas (1 paper, 2012). "In the present study, SATB1 expression was found to be up-regulated in EOC compared to tubal epithelium, from which a proportion of serous carcinomas are though to arise." (PMID 22992394, 2012).
speech disorder (1 paper, 2024). A term referring to disorders characterized by the disruption of normal speech. "In the present study, we described a new patient affected by ID, speech disorder, and EEG/MRI abnormalities, who harbors a new de novo PVT in SATB1 near to the Homeobox domain." (PMID 38790177, 2024).
Stroke (1 paper, 2010). Sudden impairment of blood flow to a part of the brain due to occlusion or rupture of an artery to the brain. "We report novel and exciting finding that presence of the motif binding Satb1 prevents - in a motif number dependent manner - transcriptional activation in the stroke system." (PMID 20565733, 2010).
tonsillitis (1 paper, 2020). Inflammation of the tonsillar tissue. "Concomitantly, SATB1 levels in UT-SCC-14 tumor xenografts were found to be only slightly elevated over normal mucosa from tonsillitis patients." (PMID 32451408, 2020).
triple-negative breast carcinoma (1 paper, 2022). An invasive breast carcinoma which is negative for expression of estrogen receptor (ER), progesterone receptor (PR), and human epidermal growth factor receptor 2 (HER2). "Some of the herbal derivatives simultaneously impede Wnt/β-catenin signaling and other overactive pathways in triple negative breast cancer, including: mTORC1; ER stress and SATB1 signaling." (PMID 36079579, 2022).
xerostomia (1 paper, 2021). Dryness of the mouth resulting from reduced salivary secretion. "In our previous study, we demonstrated that SS-like xerostomia was observed in SATB1 conditional knockout (SATB1cKO) mice, in which the floxed SATB1 gene was specifically deleted in hematopoietic cells as early as 4 weeks of age." (PMID 34576286, 2021).
tumor (126 papers, 2008 to 2026). "Current research predominantly indicates that SATB1 is linked to malignant tumors, tumor progression, and carcinogenic processes, suggesting a potential connection between SATB1 and Marek’s disease." (PMID 40559620, 2025). "Given its consistent role across multiple tumor types, SATB1 shows promise as a molecular marker for both diagnostic and prognostic testing in oncology." (PMID 40071088, 2025). "SATB1 expression is frequently associated with poor tumor differentiation, aggressive phenotypes, and reduced patient survival, making it a valuable marker for poor prognosis in these malignancies." (PMID 40071088, 2025). "Most importantly, SATB1-specific silencing in tumour-associated DCs enhanced the survival rates of ID8-Defb29/Vegf-a-challenged mice." (PMID 38136940, 2023). "For example, Stephen and associates showed that tumor-derived TGF-β activates Smad3 to increase PD-1 expression by inhibiting the chromatin organizer Satb1 in tumor-reactive T cells." (PMID 34093869, 2021). "Accordingly, Satb1 prevents premature T-cell exhaustion by controlling PD-1 expression, a pathway that is altered in cancer, causing reduced anti-tumor activity." (PMID 33761971, 2021). "A loss of SATB1′s expression in these tumours was associated with a shorter overall survival of the patients." (PMID 31450715, 2019). "SATB1′s knockdown not only reduced the growth of the tumours, but also caused pyknosis of the cell nuclei and increased apoptosis." (PMID 31450715, 2019). "The pooled OR was 1.88 (95% CI: 1.06–3.34), which implied that high expressed SATB1 was associated with decreased tumor differentiation in CRC." (PMID 29867574, 2018). "SATB1 can influence the expression of more than 1000 genes, including those implicated in the pathogenesis of human neoplasms." (PMID 25874491, 2015). "Results of many studies suggest that SATB1 overexpression is associated with an aggressive phenotype of tumor cells." (PMID 25874491, 2015). "SATB1 expression was significantly associated with microsatellite stable tumours (p < 0.001), beta-catenin overexpression (p < 0.001) and SATB2 expression (p < 0.001)." (PMID 22935204, 2012). "The authors demonstrate that SATB1 orchestrates epigenetic modifications at target loci, up-regulating metastasis associated genes and down-regulating tumour suppressors." (PMID 19642980, 2009). "Although we observed a trend for tumours with higher SATB1 mRNA expression levels to be associated with shorter OS times, this failed to reach statistical significance." (PMID 19642980, 2009). "SATB1 expression is closely associated with tumor invasion depth and disease stage." (PMID 40071088, 2025). "Additionally, SATB1 silencing in tumour-associated DCs boosted the anti-tumour immune response and delayed malignant progression." (PMID 38136940, 2023). "Moreover, SATB1 is also overexpressed in a wide array of cancers and is positively associated with increased tumor size, metastasis, tumor progression, poor prognosis and reduced overall survival." (PMID 36376298, 2022). "Accordingly, SATB1 has been found to be overexpressed in a wide range of tumors, including breast, lung, pancreas, colorectal, liver, bladder, prostate and ovarian cancer, and has been associated with tumor progression and poor prognosis." (PMID 33761971, 2021). "These initial results suggested that in AC an elevated SATB1 level may be associated with a more aggressive, malignant tumour phenotype." (PMID 31450715, 2019). "Furthermore, SATB1′s expression was found to be associated with microsatellite stable tumours and correlated with beta-catenin’s and SATB2′s levels." (PMID 31450715, 2019). "Moreover, in AC clinical samples SATB1′s expression was associated with a poor degree of tumour differentiation, whereas in the SCC subtype the level of SATB1 was increased in well differentiated tumours." (PMID 31450715, 2019).